SNORD21 (small nucleolar RNA, C/D box 21)
Synonyms: U21; RNU21
Gene: Small nucleolar RNA gene on chromosome 1 (92,837,289 to 92,837,383, forward strand). Ensembl gene ENSG00000206680.
Gene Ontology:
Biological process: RNA processing
Cellular component: nucleolus
Homologues: Orthologues: macaque SNORD21 (100% identical), dog SNORD21 (98% identical), rabbit SNORD21 (96% identical), pig SNORD21 (94% identical), rat Snord21 (91% identical), guinea pig SNORD21 (89% identical), mouse Snord21 (86% identical), guinea pig SNORD21 (80% identical), zebrafish SNORD21 (73% identical), zebrafish SNORD21 (58% identical).